BNIP3L (BCL2 interacting protein 3 like)
Diseases named in the same sentence as BNIP3L in open-access papers (continued):
Sharing a sentence is not in itself a finding about the gene and the disease.
cancer (continued). "Under such conditions, cancer stem cells are able to use FUNDC1, BNIP3 and BNIP3L/NIX proteins for energy production and, consequently, significantly reduce the amount of mitochondria in the cell through the mitophagy process." (PMID 33804163, 2021). "Recent studies have shown that the expression of a number of proteins involved in the mitophagy processes, including MFN1, Parkin, BNIP3, and BNIP3L/NIX, is dysregulated in different cancer types." (PMID 32308807, 2020). "This specific epigenetic alteration allows cancer cells to escape to BNIP3 and BNIP3L proapoptotic activity." (PMID 30223788, 2018). "A total of 8 cancer genes with an OncoScore above the 90th percentile was identified (TNFRSF10B, TNFRSF10C, TNFRSF10A, TNFRSF10D, LZTS1, NKX3-1, BNIP3L and RHOBTB2; OncoScore range: 71.4–86.3)." (PMID 28387367, 2017). "Cancer stem-cell numbers, presence of necrosis, and numbers of Ki67-, TUNEL-, BECLIN1- BNIP3L-, or LC3B-expressing cells were studied in multivariate analysis for their correlation with pCR." (PMID 28445132, 2017). "Taken together, these experiments provide the evidence of feasibility for BMK1 inhibition in the setting of cancer stem cells through BNIP3 and BNIP3L." (PMID 26432836, 2015). "Notably, PRKN exhibited the highest alteration frequency, affecting 34% of all cancer samples, followed by OPTN (21%), PINK1 (18%), SRC (15%), BECN1 (13%), MAP1LC3A (9%), and BNIP3L (5%)." (PMID 39859167, 2025). "Furthermore, BNIP3L and BECN1 expression potentially inhibited the cell cycle and DNA damage pathways (16–19%) in pan-cancer." (PMID 39859167, 2025). "Overall, these findings highlight the complex landscape of CNVs in PRKN, OPTN, PINK1, SRC, BECN1, BNIP3L, and MAP1LC3A across different cancer types, emphasizing the potential impact of these genetic alterations on cancer pathogenesis and the importance of considering CNVs in therapeutic strategies." (PMID 39859167, 2025). "Here, we conduct a comprehensive analysis of a mitophagy-related gene signature, composed of PRKN, PINK1, MAP1LC3A, SRC, BNIP3L, BECN1, and OPTN, across various cancer types, revealing significant differential expression patterns associated with molecular subtypes, stages, and patient outcomes." (PMID 39859167, 2025). "Moreover, like other well-known mitophagy receptors such as BNIP3L and FUNDC1, CLU overexpression triggers mitophagy to clear damaged mitochondria, protecting cancer cells from cisplatin-induced stress." (PMID 38447939, 2024). "In addition, integrin beta 4 (ITGB4)-overexpressing triple-negative breast cancer (TNBC) cells provide the cancer-promoting capabilities of CAFs with ITGB4 proteins via exosomes, thus enhancing BNIP3L-dependent mitophagy and producing more lactate in CAFs." (PMID 38067169, 2023). "Indeed, the mitophagy proteins BNIP3L/NIX, BNIP3, and FUNDC1 were found upregulated in response to hypoxia in cancer." (PMID 35205167, 2022). "Similarly, we observed overexpression of some critical cancer related and regulatory genes such as GADD34, DDIT4, BNIP3, BNIP3L, NOXA, and LC3B-II in response to AQ treatments confirming the role of AQ in regulating the autophagy and cancer regulatory genes." (PMID 36232751, 2022). "Thus, our results showing an attenuation in the BNIP3L expression on E-cig use raises the possibility of emergence of COPD, IPF or even cancers in these individuals." (PMID 33290406, 2020). "Nanog binds directly to the enhancer region of the BNIP3L (BCL2 Interacting Protein 3 Like) promoter during hypoxia, thereby releasing BECLIN from Bcl-2 (B-cell lymphoma 2), increasing its expression, and promoting one of the hypoxia-induced responses of cancer cells." (PMID 37569414, 2023). "KEGG pathway analysis further highlighted the role of S6K1 in cancer progression, in which the depletion of S6K1 could re-express a group of tumor suppressor genes including RASSF5, RASSF6, STAT1, CEACAM1, BNIP3L and SOCS2." (PMID 32201535, 2020).
cancer (continued). "BNIP3/NIX-mediated mitophagy contributes to the dox-resistance to CSCs in colorectal cancer and the silencing of BNIP3L both prevents mitophagy and increases the sensitivity to doxorubicin therapy, which suggests the importance of mitophagy in drug resistance for cancer therapy targeting CSCs." (PMID 32587855, 2020). "Therefore, inhibition of BMK1 pathway suppressed cancer stem cells through BNIP3 and BNIP3L." (PMID 26432836, 2015). "No homozygous deletions within BNIP3L were found in any cancer cell line (data not shown)." (PMID 12610513, 2003). "In addition, BNIP3L might be involved in mitophagy in muscle and some cancer cells, even though direct evidence is still absent." (PMID 34930907, 2021). "The mRNA expression levels of BNIP3L, C4orf3, and P4HA2 did not change statistically in the normal group and the cancer group." (PMID 41214670, 2025). "When we looked for autophagy markers in our pre-treatment biopsies of non-pCR TNBCs, we found that CD133-expressing cancer stem cells co-expressed BECLIN1, LC3B, and BNIP3L." (PMID 28445132, 2017). "At gene level, Beclin-1, p-62, BNIP3, NIX/BNIP3L and TFEB mRNAs were not significantly modulated, while LC3B and PINK1 mRNA levels were increased and decreased, respectively, in cachectic cancer patients." (PMID 27459917, 2016). "Since BNIP3 and BNIP3L promote cell death, it is not surprising that upregulation of BNIP3 and BNIP3L were reported to block cancer stem cells in multi types of cancer." (PMID 26432836, 2015).
infection (6 papers, 2008 to 2022). The state of being infected such as from the introduction of a foreign agent such as serum, vaccine, antigenic substance or organism. "In late stages of infection (24 and 48 h p.i.)the pro-apototic gene BNIP3L was down-regulated in response to all MAH infections compared to E. coli K12 stimulation (P<0.05, unpaired t test)." (PMID 21629653, 2011). "Bnip3 expression was only upregulated by a C. burnetii infection under normoxia, but not under hypoxia, while Bnip3l expression was not modulated by the infection at all." (PMID 35755850, 2022). "Four receptors (BNIP3L, Optineurin, FUNDC1, and TAX1BP1) were selectively modified upon Mtb infection; these modifications occurred in functional domains of these receptors and changed through the time course of infection." (PMID 31951200, 2020). "Moreover, in order to form NK cell memory, NK cells require Zbtb32 to undergo a proliferative burst and clonal expansion in response to infection, require BNIP3 and BNIP3L -dependent clearance of damaged mitochondria by autophagy, and require pro-apoptotic factor Bim for contraction." (PMID 32849653, 2020).
cardiac disease (4 papers, 2015 to 2025). "Altogether, EPAS1 and BNIP3L are induced in ACM and DCM hearts, underscoring the relevance of these components in cardiac disease." (PMID 40034852, 2025).
neurological disorders (2 papers, 2021 to 2026). "BNIP3L/NIX, a mitophagy receptor, has been linked to neurological disorders, yet its specific function in the brain remains unclear." (PMID 41580974, 2026). "The identification of these enzymes might bring forward promising drug targets for BNIP3L-related human diseases, particularly neurological disorders." (PMID 34930907, 2021).
metabolic disorders (1 paper, 2025). "Previous researches showed that in metabolic disorders or oxidative stress, where mitochondrial function and mitophagy are closely intertwined, PINK1 and Parkin act as central mediators, and BNIP3L is upregulated." (PMID 41334630, 2025).
BNIP3L also shares sentences with these, for which no sentence is quoted: cardiac hypertrophy (5 papers); prostate carcinoma (5); neurodegenerative disease (3); Stroke (3); acute kidney injury (2); brain diseases (2); central nervous system diseases (2); dementia (2); fatty liver (2); neuroblastoma (2); osteosarcoma (2); adenocarcinoma (1); alcohol dependence (1); amyloidosis (1); atherosclerosis (1); bacterial infection (1); brain tumors (1); breast tumours (1); cancers of the reproductive system (1); COVID-19 (1); Crohn disease (1); diabetic retinopathy (1); Encephalopathy (1); hematologic neoplasms (1); hematological malignancies (1); inflammation (1); inflammatory bowel disease (1); malignant glioma (1); memory impairment (1); metabolic syndrome (1).
A further 14 diseases each share a sentence with BNIP3L in 1 paper.